WNT11 (Wnt family member 11)
Diseases named in the same sentence as WNT11 in open-access papers (continued):
Sharing a sentence is not in itself a finding about the gene and the disease.
cancer (continued). "In contrast, luminal cancers show less consistent up-regulation of SCRIB and VANGL2 mRNAs and rare up-regulation of SMURF2 or WNT11." (PMID 36675340, 2023). "Several studies have disseminated that a number of miRs can promote EMT and cancer stemness in PDAC, whereas our current study provides some new pilot insights into the role of miR-21 depletion in cancer stemness, EMT, and the Wnt-11 pathway." (PMID 35163198, 2022). "As a contributor to TGF-β signaling pathways, Wnt11 also impacts EMT, affecting cancer cell migration and invasion." (PMID 35668332, 2022). "In both the cancer types, there was upregulation of WNT11 gene, whereas in case of LUSC WNT11 expression was downregulated." (PMID 33840169, 2021). "High expression of the putative cancer and hematopoietic stem cell marker THY1/CD90 and WNT11 and CTNNB1 also suggest potential novel therapeutic strategies to increase pCR rates." (PMID 30967156, 2019). "Elevated endogenous WNT11 increases activity of MMP2 and MMP9, and promotes proliferation, migration and invasion of cancer-derived cells." (PMID 26861754, 2016). "This study provides the first demonstration that WNT11 expression is regulated by hypoxia and the HIF-1α pathway in normal and cancer-derived cells." (PMID 26861754, 2016). "WNT11 was knocked down with lentiviral shRNAs in 4T1 or MDA-MB-231 cells, the latter of which have the highest endogenous expression of WNT11 in the cancer cell lines tested." (PMID 26861754, 2016). "For example, SFRP4, WNT11, FZD2, MYC were highly expressed in cancer tissues which represent the Wnt pathway was activiated and BCL2A1, ICM1, TNFSF14 in NF-κB pathway were highly expressed as well." (PMID 25928635, 2015). "The relative nature of Wnt11 expression was further confirmed, when Wnt11 gene transcription was measured in an AC (A549) and an SCC (H157) cancer cell line." (PMID 23505429, 2013). "Notably, the repression of β-catenin activity by WNT11 contrasts with canonical WNT signaling, highlighting the context-specific nature of WNT pathway interactions in cancer." (PMID 41426343, 2025). "Kaiso regulates Wnt/β-catenin target genes, including Wnt11, Cyclin D1, and Matrilysin 7, in various cancers (33, –, 35), but these were absent in classical VN and VP-MCC cell lines, while variant MCC cells expressed only Cyclin D1 (data not shown)." (PMID 40407323, 2025). "Wnt-11 is downstream to TGFβ, which has previously been shown to be one of the triggers of the epithelial–mesenchymal transition (EMT), as well as chemoresistance in cancer." (PMID 32605008, 2020). "P120ctn nuclear translocation could relieve Kaiso-mediated repression of several cancer-related genes, such as MMP7 or Wnt11." (PMID 24260200, 2013). "WNT11 is a positive regulator of the noncanonical Wnt signaling pathway, which plays a role in carcinogenesis including cell proliferation and migratory capacity of cancer cells." (PMID 35954313, 2022). "Our findings of the suppressive influence of 1,8-cineol on relevant components in the WNT pathway-driven cancer progression, such as GSK-3 (Ser 9/21), β-catenin, and WNT11, describe a completely novel mode of action, which may lead to novel treatment approaches of this natural drug." (PMID 28589081, 2017). "Furthermore, our previous and others’ studies indicated the inhibition of ERRα can also suppress the migration and invasion of cancer cells via suppression the epithelial-to-mesenchymal transition, down regulation the stability of RHOA or induction the expression of WNT11." (PMID 26871469, 2016). "In addition, SMURF2 mRNA, but not WNT11 mRNA, is often up-regulated in basal cancers." (PMID 36675340, 2023). "Luga and colleagues demonstrated that exosomes secreted by cancer-associated fibroblasts can instigate breast cancer cells to acquire a motile phenotype by mobilizing PCP core components such as FZD6, DVL1, VANGL1, PK1 and stimulating the autocrine secretion of the non-canonical ligand Wnt11." (PMID 28737757, 2017).
cancer (continued). "Across different tumor types, non-canonical Wnt11 signalling correlates with enhanced epithelial-mesenchymal transition (EMT) and invasive phenotypes in colorectal, pancreatic and other cancers, suggesting its tumor-type-specific immuno-remodelling potential." (PMID 41426343, 2025). "By comparing OVCAR3 control to OVCAR3 with WNT + RSPO + SFRP2, we observed pronounced global protein level changes with indications of WNT signalling activation, with significant overexpression of WNT11, a non-canonical WNT signalling molecule with a role in cancer." (PMID 38361045, 2024). "Cell morphology and p-MLC2 levels were assessed as amoeboid markers; ki-67 staining as a proliferative marker; WNT11, WNT5B and DAAM1 expression as non-canonical Wnt markers; and ALDH1A1, ALDH1A3, CD44, NANOG and OCT4 were evaluated as cancer stem cell-related markers." (PMID 33082334, 2020).
tumor (53 papers, 2008 to 2025). "These exosomes were taken up by tumor cells, providingthem with Wnt11, a signaling protein associated with tumor progression." (PMID 40771849, 2025). "Consistent with its proposed tumor-suppressive role, WNT11 overexpression has also been linked to improved survival outcomes." (PMID 41044153, 2025). "In univariate analysis, increased Wnt-11 expression was also associated with tumor invasion and increased 5-year mortality." (PMID 31261741, 2019). "Wnt-11 levels were found to be increased in a subset of tumors and this was associated with patient gender, tumor location, tumor invasion, and patient mortality." (PMID 31261741, 2019). "In addition to its roles in metastatic and tumour contexts, WNT11 has been implicated in several inflammatory and tissue-homeostatic processes." (PMID 41426343, 2025). "The same comparison associated high Wnt-11 with tumor invasion (p = 0.04)." (PMID 31261741, 2019). "Furthermore, transfection with miR-137mimics suppressed at least two downstream target genes of ERRα–CCNE1 and WNT11, which are important effectors of ERRα implicated in tumor proliferation and migration." (PMID 22723937, 2012). "In sum, targeting the WNT11/CAMKII axis offers a compelling strategy to rewire the tumor-immune interface in liver metastasis." (PMID 41426343, 2025). "Conversely, WNT11 expression was significantly downregulated in tumor samples compared with that in the corresponding control tissue, as shown by box-and-whisker plots." (PMID 41044153, 2025). "To better conceptualize the heterogeneity in WNT11-driven immune resistance across different liver metastasis origins, we propose a tumor–immune–signaling matrix, integrating primary tumor source, immune phenotypes, and dominant WNT11 downstream effectors." (PMID 41426343, 2025). "WNT11’s role in modulating the tumor microenvironment (TME) has gained considerable attention due to its dual capacity to influence both stromal and immune components." (PMID 41426343, 2025). "Combined expression of WNT ligands (WNT3A, WNT4, WNT7B, WNT9A, WNT10A, WNT11) in BRCA patient tumours has a positive correlation (R = 0.27, p value = 0) with the combined expression of key EMT-inducing transcription factors SNAI1, SNAI2, ZEB1, ZEB2 and TWIST1." (PMID 38678032, 2024). "Defects in the WNT11 gene are found in 5% of OSCC, consisting of duplications, deep deletions or punctiform mutations affecting its tumor suppressor function." (PMID 38952548, 2024). "Wnt11 has an important promoting effect on cardiac tissue proliferation and tumor cell proliferation." (PMID 38098062, 2023). "Given the similarity between synovial hyperplasia and angiogenesis in RA and cardiac tissue hyperplasia and tumor pathology, we investigated the expression changes and roles of Wnt11 in RA." (PMID 38098062, 2023). "Given that synovial hyperplasia and angiogenesis during RA have certain similarities with cardiac tissue hyperplasia and tumor pathology, we focus on the expression changes and roles of Wnt11 in RA." (PMID 38098062, 2023). "We then aimed at further elucidating the consequences of the WNT11/ROR2 interaction for tumor cell function." (PMID 34911552, 2021). "The functional consequences of WNT11/ROR2 signaling for tumor cell aggressiveness were assessed by microscopy, impedance sensing as well as viability and invasion assays." (PMID 34911552, 2021). "The gene expression profile of WNT11 between normal and primary tumor samples revealed a significant difference with a p-value of 3.043 × 10-3." (PMID 33840169, 2021). "Specifically, we find that the WNT11/5B-FZD7-DAAM1 signalling axis has an impact on tumour initiation by controlling the amoeboid phenotype." (PMID 33082334, 2020). "Immunohistochemical analysis of Wnt-11 in tumor tissues indicated that the level of Wnt-11 was elevated in 25/36 (69.4%)." (PMID 32182839, 2020).
tumor (continued). "The most likely explanation was that the SCC-Ag level is mainly determined by tumor volume and internal potential for malignancy, such as expression of gene Wnt-11, which cannot be well described by the TNM staging system." (PMID 32456707, 2020). "Analysis of Wnt-11 levels with respect to patient and tumor characteristics resulted in a number of interesting observations." (PMID 31261741, 2019). "Wnt-11 expression in tumors was heterogeneous, with some tumor cells showing intracellular staining and others showing very strong staining at cell–cell contacts." (PMID 31261741, 2019). "WNT11 expression was also elevated in tumors in a comparison of paired tumor samples and normal adjacent mucosa from a cohort of 98 patients and 50 healthy colon mucosae (GSE44076) using the Colonomics web tool (colonomics.org)." (PMID 31261741, 2019). "WNT11 mRNA expression has been reported to be upregulated in an analysis of 133 primary colorectal tumors and 41 non-tumor tissues from a Japanese cohort, correlating with recurrence after surgery." (PMID 31261741, 2019). "This revealed significantly higher levels of FZD8 and Wnt-11 in tumor cells, compared to in benign epithelium and correlations in the levels of FZD8 and Wnt-11 in benign and tumor epithelia and stroma." (PMID 29717114, 2018). "After validation of the WNT11 antibody, we observed that WNT11 is elevated in the area of tumor hypoxia where HIF-1α and pimonidazole staining are colocalized." (PMID 26861754, 2016). "Comparative analysis of gene expression in AC and SCC tumour tissues has additionally identified Wnt11 and its receptor Fzd-7 as potential regulators of SCC development." (PMID 23505429, 2013). "Our studies using primary pulmonary epithelial tissues as well as cell lines identified Wnt5a and Wnt11 as regulators of cadherin expression, most likely the “cadherin switch” that is a characteristic marker of tumour progression." (PMID 23505429, 2013). "The results emphasized that Wnt11 is necessary for the normal homeostasis of the tissue and its increased expression in the tumour correlates with the carcinogenic process." (PMID 23505429, 2013). "Immunohistochemical analysis of Wnt-11 in tumour tissue arrays indicated that the level of Wnt-11 was elevated in 77/117 (66%) of tumours, with particularly strong staining in 28/117 (24%) of cases." (PMID 20219091, 2010). "Despite challenges related to pathway complexity and tumor heterogeneity, this mini review synthesizes recent advances in understanding the WNT11-driven tumor-immune axis and proposes a translational roadmap for combination strategies to overcome ICB resistance in liver metastasis." (PMID 41426343, 2025). "Conversely, WNT11 exhibited significantly increased methylation in tumor tissues, resulting in stable transcriptional repression, reduced expression, and potential impairment of its tumor-suppressive function." (PMID 41044153, 2025). "Our findings suggest that WNT2 and WNT7B act as potential oncogenic drivers, whereas WNT11 may serve as a tumor suppressor." (PMID 41044153, 2025). "Importantly, WNT11 expression and function appear to be highly context-dependent across tumor types." (PMID 41426343, 2025). "Emerging evidence indicates that WNT11 may influence the tumor-immune interface by modulating cytotoxic T=cell infiltration and macrophage polarization." (PMID 41426343, 2025). "Expanding research into WNT11-mediated immune remodeling in diverse tumor contexts could uncover shared or unique resistance mechanisms, broadening the therapeutic scope of this target." (PMID 41426343, 2025). "Further investigation is warranted to determine whether WNT11 amplification represents a compensatory response or byproduct of genomic instability during tumor development." (PMID 41044153, 2025). "Wnt5 and Wnt11 can have both oncogenic and tumour-suppressive functions." (PMID 36766788, 2023).
tumor (continued). "Non-canonical Wnt-11 overexpression is associated with poor prognosis and tumor-node-metastasis (TNM) staging in PDAC." (PMID 35163198, 2022). "We found that high Wnt11 expression indicates poor outcomes in AML patients with chemotherapy only, suggesting that high Wnt11 expression may be involved in leukaemogenesis as a tumour promoter." (PMID 33417298, 2021). "α-catenin is a tumor suppressor involved in Wnt11,24, Hippo-Yap6,7 and NF-κB signaling pathways." (PMID 29540699, 2018). "WNT6 and WNT11 encode Wnt ligands that have potential tumor-promoting roles even in CRCs with APC mutations and that have the capability to signal to the stromal components to modulate the tumor microenvironment." (PMID 24651522, 2014). "Wnt11 was detected in both normal and cancerous samples, although at higher levels in the tumours." (PMID 23505429, 2013). "Therefore it is possible that the Wnt-11-positive tumours from patients with high PSA levels contain an androgen-independent population of tumour cells." (PMID 20219091, 2010). "While WNT11 is implicated in CD8+ T-cell exclusion and macrophage polarization in LM, its expression levels and downstream signaling strength may vary significantly across tumor types and individuals." (PMID 41426343, 2025). "Finally, the growth of large, solid tumor microtissues on RGD-free HAGM cryogels, along with HA-mediated CD44 activation, is probably responsible for the overexpression of genetic markers for hypoxia and tumor aggressiveness, including HIF1α, WNT-11, BCL2, CD73, and VEGF." (PMID 35198956, 2022). "Wnt11 might function as a tumor suppressive gene that can inhibit Wnt signaling." (PMID 32053894, 2020). "In addition, Wnt-11 was found to be highly expressed in tumor cells from a CRC liver metastasis." (PMID 31261741, 2019). "In addition, we observed decreased tumor growth in mice injected with 4T1 cells expressing shRNAs against Wnt11, and reduced proliferation in WNT11 knockout cells in vitro, suggesting that impaired tumor progression in Wnt11 shRNA allograft is secondary to reduced proliferation." (PMID 26861754, 2016). "Our results show that miR-137, a potential tumor suppressor microRNA, can negatively modulate the expression of ERRα and suppress the growth and migration of breast cancer cells partly through two immediate downstream effectors of ERRα-cell cycle protein cyclinE1 and WNT11." (PMID 22723937, 2012). "However, Wnt-11 was significantly elevated in tumours from patients with PSA levels above 10 ng/ml." (PMID 20219091, 2010). "High expression of lncABHD11-AS1 was associated with poor overall survival in CRC patients, and it acts as a molecular sponge for miR-1254 targeting wnt11 to accelerate CRC cell proliferation, invasion and tumor growth." (PMID 37587207, 2023). "On the contrary, Kaiso has also been suggested to be a potential tumour suppressor, which repressed the transcription of MMP7, CCND1 and WNT11 genes involved in oncogenesis and metastasis." (PMID 35851744, 2022). "We identified WNT11 as a ligand for human ROR2 that activates WNT/PCP signaling and is responsible for the induction of tumor invasion." (PMID 34911552, 2021). "It has been shown that β-catenin can regulate WNT11, Cyclin D1, and MMP7 in many tumor cells, and so we next examined the role of CTNND1-mediated modulation of these genes." (PMID 27193094, 2016). "WNT2 and WNT11, which are positively correlated with immune scores in BRCA, are key players in TME modulation and may affect tumor progression and immune evasion." (PMID 41044153, 2025). "Targeting the WNT11/CAMKII axis could simultaneously reverse immune exclusion and reprogram macrophages to support anti-tumor immunity, thereby overcoming two major bottlenecks in immunotherapy." (PMID 41426343, 2025). "The integration of WNT11-targeted strategies could synergize with existing modalities such as PD-1/PD-L1 inhibitors, CAR-T cell therapy, or tumor vaccines, to produce more durable and systemic immune responses." (PMID 41426343, 2025).
tumor (continued). "Although there were areas where tumor cells expressed high levels of both Wnt-11 and β-catenin, other areas did not." (PMID 31261741, 2019). "This review therefore focuses on the emerging WNT11/CAMKII axis as a newly identified immune resistance pathway in liver metastasis, and discusses its mechanistic roles, clinical implications, and therapeutic potential in reshaping the metastatic tumor microenvironment." (PMID 41426343, 2025). "Unlike canonical Wnt signaling, which primarily signals through β-catenin stabilization, WNT11 may antagonize β-catenin activity in certain contexts, suggesting intricate crosstalk between non-canonical and canonical Wnt cascades in tumor immunity." (PMID 41426343, 2025). "Indeed, Wnt ligand signaling plays a key role in PDAC progression and therapeutic resistance, and tumor-proximal fibroblasts are seen to be strong contributors to the Wnt ligand pool with high level expression of the ligands WNT5A, WNT11, WNT2, WNT5, WNT5A, and WNT5B." (PMID 37350578, 2023). "However, it remained unknown whether WNT11 can also interact with ROR2 in humans and whether it might be responsible for its tumor-supporting function." (PMID 34911552, 2021). "In particular, Wnt-11 is a secreted protein that modulates cell growth, differentiation, and morphogenesis during development; however, the prevalence of increased expression of Wnt-11 in tumours and the functions of Wnt-11 in PCa cells are not fully understood." (PMID 23738079, 2013).
bacterial infection (3 papers, 2019 to 2025). "Wnt11 signaling protects the host from bacterial infection and inhibits apoptosis in intestinal cells." (PMID 31736969, 2019). "WNT11 expression can be induced by many factors, including TGF-β, retinoic acid and β-catenin, and by environmental changes, such as hypoxia and bacterial infection." (PMID 31261741, 2019).
infection (2 papers, 2019 to 2025). The state of being infected such as from the introduction of a foreign agent such as serum, vaccine, antigenic substance or organism. "The relative expression of the Wnt11 gene was significantly upregulated after infection with V. parahaemolyticus in Li." (PMID 40941351, 2025). "They found that infection of host epithelial cells with S. typhimurium leads to an elevated expression of Wnt11, dependent on the Salmonella effector protein AvrA." (PMID 31497020, 2019). "Further, the in vivo studies showed a relocalization of Wnt11 to the lower crypts during infection and also demonstrated that overexpressing Wnt11 shows inhibitory effects on Salmonella internalization and IL-8 expression-mediated intestinal inflammation." (PMID 31497020, 2019).
hematological cancers (1 paper, 2022). "WNT5b and WNT11 have been shown to regulate the non-canonical WNT pathway in non-hematological cancers." (PMID 35246138, 2022).